TLR4 (toll like receptor 4)
Diseases named in the same sentence as TLR4 in open-access papers (continued):
Sharing a sentence is not in itself a finding about the gene and the disease.
lung cancer (continued). "Studies showed that E. coli induce lung cancer cell movement, adherence, and metastasis through Toll-like receptor 4 (TLR4) signaling via suppressing TLR4 (Eritoran), p38 mitogen-activated protein kinases (MAPK), and extracellular signal-regulated kinase (ERK1/2) phosphorylation." (PMID 35885645, 2022). "Having found that USP15KO A549 and USP15KO H1299 lung cancer cells exhibited increased cancer invasion, we further examined whether USP15 affected lung cancer migration and invasion through autophagy induction by TLR4 stimulation." (PMID 35422093, 2022). "TLR4 is specifically shown to help lung cancer cells escape the immune system through the release of immunosuppressive cytokines like transforming growth factor beta (TGF-β), VEGF, and IL-8, while also increasing resistance to proapoptotic factors like tumor necrosis factor-alpha (TNF-α)." (PMID 36389785, 2022). "As we have demonstrated that the autophagy activity contributes to CAFs’ effect on the activation of TLR4/NF-κB pathway in lung cancer cells, we further investigated whether HMGB1 is involved in this event." (PMID 34552063, 2021). "Interestingly, quercetin and chrysin inhibit lung cancer invasion and migration through downregulation of TLR4/NF-κB signaling." (PMID 34552063, 2021). "In addition, TLR4 signaling promotes proliferation of A549 lung cancer cells through PTGS2/COX-2 (prostaglandin-endoperoxide synthase 2 (prostaglandin G/H synthase and cyclooxygenase)) and epidermal growth factor receptor (EGFR) activation." (PMID 32384667, 2020). "TLR4 activated by fucoidan induces ROS-associated ERS by activating the PERK–ATF4–CHOP pathway and promotes caspase-3 activation through the TLR4–ERS–CHOP pathway, resulting in apoptosis in lung cancer cells." (PMID 32707775, 2020). "Besides, Oligo-Fucoidan supplementation sensitizes lung cancer cell cytotoxicity induced by cisplatin via stimulation of TLR4/CHOP-mediated caspase-3 and PARP activity that prevent tumor development in mice." (PMID 32059469, 2020). "Herein, we investigated whether TLR4 is another component of the upstream regulatory signaling of NEAT1 expression in lung cancer cell lines." (PMID 29788922, 2018). "Thus, the effect of elevated TLR4 on prognosis in patients with lung cancers needs to be further confirmed." (PMID 29560134, 2018). "Given that Galactin-3 positively regulates TLR4 protein expression, as well as the proliferation and migration of lung cancer cell lines; next, we investigated whether Galectin-3 acts through TLR4/NF-κB/NEAT1." (PMID 29788922, 2018). "In lung cancer cells, LPS-triggered TLR4 activation enhances the secretion of IL-10." (PMID 28881826, 2017). "Previous studies also indicated that LMF promotes TGF-β receptor degradation and induces Toll-like receptor 4-regulated reactive oxygen species that promotes endoplasmic reticulum stress-mediated apoptosis in lung cancer cells, thus inhibiting lung cancer progression." (PMID 28928376, 2017). "All the current findings indicated that TLR4 was a valuable predicting marker that might provide help for clinicians to design effective therapeutic modality against lung cancer." (PMID 28484456, 2017). "With lung cancer cells it has been shown that TLR4-signalling promoted resistance towards TRAIL-induced apoptosis and that this effect could be induced by LPS-stimulation." (PMID 28572836, 2017). "Our studies using primary mouse lung cancer models have demonstrated a protective nature of TLR4 that resulted in reduced tumor numbers, specific macrophage populations, myeloid-derived suppressor cells (MDSCs), and neutrophils, among other inflammatory cell types." (PMID 29190881, 2017). "TLR4 was readily detectable in these primary human lung cancer cells and could be up-regulated by LPS stimulation." (PMID 27286259, 2016). "Further, TLR4 activation in primary human lung cancer cells increased their ROS levels." (PMID 27286259, 2016).
lung cancer (continued). "TLR4 expressed on human lung cancer cells is functionally active, and may play important roles in promoting immune escape of human lung cancer cells by inducing immunosuppressive cytokines and apoptosis resistance." (PMID 26675260, 2016). "Knockdown of TLR4 blocked the enhanced tumor growth of primary human lung cancer in vivo." (PMID 27286259, 2016). "Speculatively, HSP90 inhibitors may have an adjunctive role with immune checkpoint inhibitors given that in lung cancer TLR4 engagement promotes escape from immune tumour killing by increasing resistance to apoptosis and inducing immune suppressing cytokines." (PMID 25615645, 2015). "In contrast, in a two-stage chemical carcinogenesis mouse model, in which inflammation mediated the promotion phase of lung cancer, the presence of a functional TLR4 was shown to inhibit lung carcinogenesis, suggesting a protective role of TLR4 in this model of cancer." (PMID 20618976, 2010). "Interestingly, a different fucoidan from Fucus vesiculosus could activate the TLR4- mediated reactions, leading to apoptosis of lung cancer cells." (PMID 36768552, 2023). "Having shown that USP15 negatively regulated lung cancer migration and invasion induced by TLR4 stimulation through inhibition of autophagy induction, we next explored the molecular mechanism in which USP15 was implicated in autophagy induction by TLR4 stimulation." (PMID 35422093, 2022). "Notably, TLR4/5/7/8 and 9 are specifically overexpressed in lung cancer tissues." (PMID 36419877, 2022). "TLR4 directly interacts with the environment, which may have a contributing effect on lung cancer." (PMID 32351566, 2020). "Indeed, TLR4 stimulation by LPS increased production of immunosuppressive cytokines, possibly contributing to tumor immune escape, and induced resistance to apoptosis in lung cancer cells." (PMID 31695691, 2019). "Moreover, the cell proliferation and migration of lung cancer cell were significantly suppressed by Galectin-3 knockdown while promoted by Galectin-3 overexpression, indicating the potential role of Galectin-3 in activating TLR4 signaling and promoting lung cancer progression." (PMID 29788922, 2018). "The resistin effect also stimulates the TLR4/Src/EGFR/PI3K/NF-κB pathway, which in turn leads to lung cancer metastasis." (PMID 40727443, 2025). "This figure presents a detailed analysis of immune responses and genomic states across different cell types in lung cancer, focusing on three key genes: CCR7, TLR4 and TLR2." (PMID 41319095, 2025). "Our analysis identified six key immune regulatory genes (TLR2, TLR4, CCR7, IL18, TIRAP and FOXP3) that show differential expression between lung cancer and normal tissues and demonstrate potential prognostic value." (PMID 41319095, 2025). "Six key immune genes (TLR2, TLR4, CCR7, IL18, TIRAP and FOXP3) showed cell‐type specific expression patterns in the lung cancer microenvironment." (PMID 41319095, 2025). "Altogether, our current data suggest that ARRB2 can negatively regulate lung cancer progression by inhibiting TLR3- and TLR4-induced autophagy." (PMID 37443143, 2023). "TLRs have been shown to be overexpressed in different cancers, such as TLR7 and TLR8 in pancreatic cancer; TLR3, TLR4, TLR7, and TLR9 in esophageal cancer; TLR4, TLR5, and TLR7–9 in lung cancer; and TLR2–5 in ovarian cancer." (PMID 36890302, 2023). "Our results also demonstrate that ARRB2 can negatively regulate the TRAF6-TAB2 signaling axis for NF-κB activation and the TRAF6-BECN1 signaling axis for autophagy induction, thereby attenuating lung cancer progression induced by TLR3 and TLR4." (PMID 37443143, 2023). "Another study showed that, in lung cancer, tumor-dependent complement 5a increases the expression of the HMGB1 receptors TLR4 and RAGE (advanced glycation end products) on PMN-MDSCs, promoting their neutrophil extracellular trap (NET) generation." (PMID 36911674, 2023).
lung cancer (continued). "Taken together, these results suggest that ARRB2 can functionally inhibit the migration, invasion, colony formation, and proliferation of lung cancer cells induced by TLR3 and TLR4 stimulation." (PMID 37443143, 2023). "Recently, it has been reported that autophagy can facilitate TLR4- and TLR3-triggered migration and invasion of lung cancer cells through the promotion of TRAF6 ubiquitination." (PMID 37443143, 2023). "A previous study revealed that NETs were produced by neutrophils in a toll-like receptor 4 (TLR4) and high-mobility group box 1 (HMGB1)-dependent manner in lung cancer cells." (PMID 34476216, 2021). "We further checked the expression levels of TLR4 and MOR in human lung cancer cell lines with different pathologies including A549 (ADC), H1299 (ADC), H520 (SCC), H1703 (SCC), H446 (small cell lung cancer), and H460 (large cell lung cancer)." (PMID 33628591, 2021). "Collectively, our results show that autophagy-dependent HMGB1 release by CAFs was responsible for stimulating the metastatic potential of lung cancer cells by the activation of the NF-κB signaling pathway, possibly via the interaction of HMGB1 with TLR4." (PMID 34552063, 2021). "Conversely, seven of the downregulated hub genes (TLR4, PECAM1, SELP, CXCL12, VWF, KDR, and CD34) showed both low expression and good prognosis in lung cancer patients (p < 0.05)." (PMID 33627711, 2021). "Foxp3 expression, controlled by activated Toll-like receptor 4 (TLR4), enhances immunosuppressive functions of Tregs by inducing inhibitory cytokine secretion and facilitate lung cancer cells to escape the immune system." (PMID 32354028, 2020). "Several studies showed that TLR2, TLR4, and TLR9 are overexpressed in lung cancer tissue compared to normal lung tissue." (PMID 32351566, 2020). "Fucoidan upregulates toll-like receptor 4 (TLR4)/CHOP-mediated caspase-3 and poly (ADP-ribose) polymerase (PARP) stimulation to promote anti-cancer effects of cisplatin in human lung cancer cells." (PMID 31936539, 2020). "The activation of NF-κB and MAPK signaling after TLR4 and TLR3 stimulation has been demonstrated to promote invasion of lung cancer cells." (PMID 33036630, 2020). "Tumor promoting inflammation is also a hallmark of cancer and our laboratory and many others have established a role for inflammatory pathways, such as TLR4, TNF, NFκB, among many others, in lung cancer development." (PMID 31018556, 2019). "It has been reported that autophagy promotes TLR4- and TLR3-induced migration and invasion of lung cancer cells." (PMID 31620128, 2019). "Fucoidan upregulates TLR4/CHOP-mediated caspase-3 and PARP activation and enhances cisplatin-induced cytotoxicity in human lung cancer cells." (PMID 31041568, 2019). "For example, activation of TLR4 and TLR3 by LPS and polyinosinic–polycytidylic acid, respectively, induced autophagy in macrophages and lung cancer cells." (PMID 29752434, 2018). "Our primary finding, that alveolar macrophages show decreased transcriptional and secretional TLR4 mediated NLRP3 activation markers, suggests that in human lung cancer innate immune responses in alveolar macrophages are compromised." (PMID 30365491, 2018). "HMGB1 secretion leads to a higher growth and invasive potential of lung cancer cell lines dependent of RAGE and TLR4 signaling." (PMID 29472602, 2018). "TLR4 and TLR9 increase miRNA expression of miR-21 and miR26a, respectively, in a xenograft model or primary human lung cancer cells." (PMID 29190881, 2017). "Our results demonstrated that knockdown of TLR4 abolishes fucoidan-induced ROS levels and CHOP expression, indicating TLR4 involvement in fucoidan-induced ROS generation and ER stress in lung cancer." (PMID 28332554, 2017). "A recent study has shown that autophagy facilitates toll-like receptor (TLR) 4 (TLR4)- and TLR3-triggered migration and invasion of lung cancer cells through promoting TRAF6 ubiquitination." (PMID 29326710, 2017).
lung cancer (continued). "It is worth noting that autophagy induced by TLR4 signaling promotes TLR-triggered cytokine production, which accelerates migration and invasion of lung cancer cells." (PMID 29285270, 2017). "We showed that fucoidan inhibits tumor viability by activating the TLR4/ROS/ER stress axis and the downstream PERK-ATF4-CHOP pathway, leading to apoptosis and suppression of lung cancer cell progression." (PMID 28332554, 2017). "We incubated HEK-Blue cells expressing human TLR2, TLR3, TLR4, TLR5, TLR7, TLR8, TLR9, or the intracellular PRR protein NOD2 with 100 μg/ml DRibbles derived from the mycoplasma free lung cancer cell line UbiLT3." (PMID 27490927, 2016). "Combing these results suggested that TLR4 activation in response to LPS led to enforced NADPH oxidase 1 activity, which in turn increased ROS production and human lung cancer progression." (PMID 27286259, 2016). "In this study, we demonstrated that ARRB2, a multifunctional cellular adaptor protein capable of regulating cellular signaling pathways, could functionally regulate lung cancer progression induced by TLR3 and TLR4 through inhibition of NF-κB and autophagy." (PMID 37443143, 2023). "In addition, a previous report has shown that autophagy can facilitate TLR4- and TLR3-triggered migration and invasion of lung cancer cells by promoting TRAF6 ubiquitination." (PMID 37443143, 2023). "Engagements of TLR3/TLR4 can induce the activation of NF-κB through the TRAF6-TAB2 signaling axis (left) and autophagy through the TRAF6-BECN1 signaling axis (right), eventually facilitating lung cancer progression." (PMID 37443143, 2023). "Notably, ARRB2-knockout (ARRB2KO) lung cancer cells exhibited marked enhancements of cancer migration, invasion, colony formation, and proliferation in response to TLR3 and TLR4 stimulation." (PMID 37443143, 2023). "In terms of function aspects, ARRB2KO lung cancer cells showed marked enhancements of autophagy and cancer progression including migration, invasion, colony formation, and proliferation in response to TLR3 and TLR4 stimulation." (PMID 37443143, 2023). "Regarding the cellular function of USP15 in lung cancer progression, notably, USP15KO A549 and USP15KO H1299 lung cancer cells exhibited increases in cancer invasion that were markedly enhanced in response to TLR4 stimulation after treatment with LPS." (PMID 35422093, 2022). "Autophagy induced by TLR4 or TLR3 activation can enhance the production of cytokines such as IL-6, CCL2, MMP2, and CCL20 by promoting TRAF6 ubiquitination, thus facilitating the migration and invasion of lung cancer cells." (PMID 35422093, 2022). "In addition, activation of TLR2 and TLR4 induce extracellular matrix remodeling and Epithelial Growth Factor Receptor (EGFR)-mediated signaling, respectively, stimulating lung carcinoma progression." (PMID 35742983, 2022). "Interestingly, recent reports have demonstrated that TLR4 and TLR3 signals induce autophagy activation, and promote migration and invasion of lung cancer cells through TRAF6 ubiquitination and MAP3K7 activation." (PMID 32384667, 2020). "The activation of toll-like receptor 4 (TLR4) signalling is suggested as a key mechanism of gram-negative bacteria in lung cancer progression." (PMID 32533048, 2020). "Furthermore, a recent report has shown that autophagy functions to TLR4- and TLR3-triggered progression of lung cancer cells through enhancing TRAF6 ubiquitination, indicating the pivotal role of autophagy in cancer progression." (PMID 31620128, 2019). "Herein, we hypothesized that Galectin-3 may activate TLR4/NF-κB/NEAT1, thereby affecting lung cancer cell proliferation and migration." (PMID 29788922, 2018). "Activation of Toll-like receptor 4 (TLR4) signaling conferred the function of gram-negative bacteria in lung cancer progression." (PMID 29568370, 2018). "As such, activation of TLR4 or TLR9 enhanced growth and metastasis of lung cancer." (PMID 29568370, 2018).
lung cancer (continued). "We revealed that Galectin-3-induced TLR4 signaling activation is involved in miR-548c regulation of lung cancer cell proliferation (data not shown)." (PMID 29788922, 2018). "What need to be noted is that in stage III lung cancer, the predicting role and the relationship between sTLR4 and cancer cell expressed TLR4 with patients’ survival was not obvious." (PMID 28484456, 2017). "Here we also found that fucoidan activation of TLR4 and TLR4-mediated ROS-induced ER stress (PERK-eIF2α-ATF4-CHOP pathway), which involved in fucoidan-induced apoptosis (activation of caspase 3 and PARP) of lung cancer cells." (PMID 28332554, 2017). "Expression of Toll-like receptor 4 (TLR4), which recognizes LPS from Gram-negative bacteria, was increased and reflected disease progress of lung cancer patients." (PMID 27286259, 2016). "Silencing TLR4 signalling in tumour cells results in reduced tumour formation, and the inhibition of tumour-cell apoptosis by TLR-signalling was also observed in ovarian, lung cancer, and myeloma cells." (PMID 20145615, 2010). "Next, we examined whether ARRB2 was involved in lung cancer progression induced by TLR3 and TLR4." (PMID 37443143, 2023). "Consequently, ARRB2 can inhibit lung cancer progression regulated by two signaling axes, TRAF6-TAB2 signaling axis for NF-κB activation and the TRAF6-BECN1 signaling axis for autophagy induction, in response to TLR3 and TLR4 stimulation." (PMID 37443143, 2023). "Importantly, USP15-knockout (USP15KO) A549 and USP15KO H1299 lung cancer cells generated by CRISPR-Cas9 gene editing showed increases of cancer migration and invasion accompanied by enhanced autophagy induction in response to TLR4 stimulation." (PMID 35422093, 2022). "Importantly, USP15-knockout (USP15KO) A549 and USP15KO H1299 lung cancer cells generated with CRISPR-Cas9 gene-editing technology showed increases in cancer migration and invasion with enhanced autophagy induction in response to TLR4 stimulation." (PMID 35422093, 2022). "TLR4 is seen at high levels of lung cancer tissue compared to non-lung cancer tissues." (PMID 36389785, 2022). "IRF1 is downregulated in lung cancer, IPF and PAH datasets, probably because it represses the expression of genes involved in anti-proliferative response, such as BIRC5/survivin, CCNB1, CCNE1, CDK1, CDK2 and CDK4 and in immune response, such as FOXP3, IL4, ANXA2 and TLR4." (PMID 31867044, 2019). "Additionally, activation of TLR4 and TLR3 stimulated autophagy induction in lung cancer cells and induced enhancements of cytokine productions, such as IL-6, CCL2/MCP-1, CCL20/MIP-3α, VEGFA, and MMP2, by encouraging TRAF6 ubiquitination, thereby led to increases of cell migration and invasion." (PMID 31620128, 2019). "However, the relationship of TLR4 expression level and survival status of lung cancer patients was not studied." (PMID 28484456, 2017). "In our current study, we demonstrate that fucoidan (i) promotes apoptosis of lung cancer cells, (ii) reduces lung tumorigenesis, (iii) induces ATF4 and CHOP protein expression in an LLC1-xenograft mice model via continuous oral feeding of fucoidan, and (iv) induces ROS-mediated ER stress via TLR4." (PMID 28332554, 2017). "Furthermore, previous research suggests that MRSA infection may enhance metastatic potential in non–small cell lung cancer cells via Toll-like receptor 4/myeloid differentiation factor 88 signaling, implying a potential vicious cycle between MRSA infection and poor prognosis in lung cancer." (PMID 41146341, 2025). "Moreover, stimulation with TLR4 and TLR3 can induce the production of IL-6, CCL2/MCP-1, CCL20/MIP-3α, VEGFA (vascular endothelial growth factor A), and MMP2 known to play pivotal roles in the migration and invasion of lung cancer cells through induction of autophagy." (PMID 37443143, 2023).